LYPD3 (LY6/PLAUR domain containing 3)
Diseases named in the same sentence as LYPD3 in open-access papers (continued):
Sharing a sentence is not in itself a finding about the gene and the disease.
tumor (29 papers, 2003 to 2025). "Some of the marker genes of these clusters were associated with tumor progression, such as LYPD3 and LY6G6D." (PMID 36816947, 2023). "Also, studies have found that LYPD3 is consistently associated with tumor progression and wound healing." (PMID 35360840, 2022). "Interestingly, AGR2 and AGR3 have both been shown to interact with the protein C4.4A (LYPD3), a factor implicated in tumour progression." (PMID 25875093, 2015). "The CCK8 assay demonstrated that LYPD3 overexpression promoted the proliferation of LUAD cell lines, while LYPD3 knockdown impeded tumor growth." (PMID 40084259, 2025). "Among upregulated genes in PDOs derived from basal-like tumors were genes that have been associated with tumor progression or cell survival including BAG3 (log-rank p = 0.0015), DUSP14 (log-rank p = 0.014), and LYPD3 (log-rank p = 0.013)." (PMID 39363341, 2024). "We also found that LYPD3 was co-expressed with S100A9 and associated with immunosuppressive tumor microenvironment (TME)." (PMID 37924160, 2023). "Together, the results suggest that JUP/AGR2/LYPD3 signaling plays a role in maintaining tumor cell stemness and enhances the glycolytic phenotype." (PMID 37924160, 2023). "We first demonstrated in vivo that upregulation of JUP levels significantly increased tumor growth rate and weight compared to controls, and that this effect was partially reversed by sh-LYPD3 (P < 0.05)." (PMID 37924160, 2023). "It is also well documented that LYPD3 can specifically be involved in tumor cell invasion through its interaction with the extracellular matrix." (PMID 35360840, 2022). "The results showed that RPS6KA1, PDGFD, APOL1, and LYPD3 are all upregulated in tumor tissues, which were consistent with GEPIA2." (PMID 36225190, 2022). "The protein expression level of LYPD3 was remarkedly elevated in tumor samples compared to that in adjacent normal tissues." (PMID 34872577, 2021). "LY6D, LY6E, PLAUR, PSCA, CD59 and LYPD3 mRNA expression was significantly increased in the PDAC tumor tissues than normal adjacent tissues (p < 0.01)." (PMID 33613843, 2021). "Among the four signature genes, only expression of LYPD3 was abnormally elevated in tumor samples compared with normal tissues in GEPIA2, which was further confirmed by IHC in our TMA." (PMID 34872577, 2021). "Multiple studies show that secreted AGR2 contributes to tumor growth and progression, particularly through its role in angiogenesis and as a ligand for cell surface receptors, including C4.4A and LYPD3." (PMID 40867591, 2025). "Despite employing multiple models and experiments to substantiate the significant role of the METTL3/miR-151-5p/LYPD3 axis in enhancing the metastatic potential of HNSCC, it is essential to recognize that this represents only one potential mechanism underlying tumor metastasis." (PMID 39009906, 2024). "In addition, our comprehensive evaluation of LYPD3 expression and phenotypic traits across a spectrum of cell lines has indicated the plausible tumor-suppressive nature of LYPD3 in HNSCC cells." (PMID 39009906, 2024). "This wonderful phenomenon links LYPD3 to the process of tumor infiltration." (PMID 37924160, 2023). "However, only LYPD3 was dramatically overexpressed in tumor tissues compared with normal tissues (P < 0.05) in GEPIA2, which combined TCGA and GTEx data together to assess the gene expression between normal and tumor tissues more accurately." (PMID 34872577, 2021). "In addition, the tumour AT2 cells were noted to express more LYPD3 compared to background AT2 cells (log2FC = 2.04, Padj = 0.039), an adhesion protein which has previously been connected to poor prognosis in NSCLC and is currently being targeted in preclinical and clinical studies." (PMID 38782901, 2024).
tumor (continued). "Considering that we have demonstrated the regulatory function of LYPD3 on the maintenance of tumor cell stemness, and that CSCs are usually accompanied by increased expression of immunosuppressive pathways, we speculated that LYPD3 may be an immunosuppressive factor." (PMID 37924160, 2023). "LYPD3 is a protein that supports cell migration and may be involved in tumor progression." (PMID 33446256, 2021). "ITGA8 and ADAMTS8 were downregulated in tumor tissues, whereas FERMT1, CTSV, CPS1, ENTPD2, SERPINB5, and LYPD3 were upregulated in tumor tissues." (PMID 35557945, 2022). "We can find that the expression of GNG7, MXRA7, ASB2, and PDGFD in tumor samples is significantly lower than that in normal samples, while the expression of RPS6KA1, CHMP4C, APOL1, and LYPD3 is reverse." (PMID 36225190, 2022). "Moreover, targeting LYPD3 (LY6/PLAUR domain containing 3), which is regulated downstream of FOXA1 and GRHL2, can reduce tumor proliferation in cases that resist endocrine treatments." (PMID 40290121, 2025). "Subsequent evaluation of these candidates’ expression in normal oral keratinocytes and HNSCC cell lines revealed comparatively lower expression levels of LYPD3 in HNSCC cell lines, suggesting its candidacy as a tumor suppressor gene correlating with the oncogenic role of miR-151-5p." (PMID 39009906, 2024).
cancer (16 papers, 2003 to 2025). A tumor composed of atypical neoplastic, often pleomorphic cells that invade other tissues. "But the LYPD3 expression level was associated with short progression-free survival (PFS) in both cancer types using the TCGA database." (PMID 36816947, 2023). "Herein, we investigated LYPD3-associated cancer biology functions." (PMID 37924160, 2023). "In a Bolivian cohort study, high urine levels of LYPD3 were found to be a cancer risk factor." (PMID 36225190, 2022). "Thus, the association between LYPD3 and cancer development is receiving increasing scientific attention and is well worth investigating." (PMID 35360840, 2022). "While LYPD3’s role in cancer is becoming more defined, additional studies are needed to confirm its involvement in cancer development or progression." (PMID 41358202, 2025). "Open Targets software showed that LYPD3 plays an important regulatory role in cancer or benign tumor." (PMID 37924160, 2023). "Using linear regression models adjusted for age, urinary osmolality, and urinary leukocytes, we identified associations between B-As and four putative cancer-related proteins: FASLG, SEZ6L, LYPD3, and TFPI2." (PMID 33381488, 2020). "Using multiplex proteomic methods in urine samples, we identified four putative cancer-related proteins (FASLG, SEZ6L, LYPD3, and TFPI2) associated with arsenic exposure in women living around Lake Poopó, Bolivia." (PMID 33381488, 2020). "The regulation of ADRβ2 signalling by LYPD3 and its metastasis promoting activities, reveal LYPD3 as a promising therapeutic target in the treatment of breast and other cancers." (PMID 32098331, 2020). "This suggests that LYPD3 could be a potential therapeutic target in multiple different cancers." (PMID 33446256, 2021). "In our previous studies, we also showed that LKB1-deficiency led to CRTC activation of many CREB-dependent genes, including NR4A2, PTGS2 (aka COX-2), LYPD3, INSL4, and LINC00473, which play important roles in cancer cell growth, survival or invasive properties." (PMID 34142658, 2021).
kidney diseases (1 paper, 2020). "We were not able to find studies reporting the participation of LYPD3 (LY6/PLAUR Domain Containing 3, also known as C4.4A), a urokinase-type plasminogen activator receptor (uPAR) homolog, in kidney diseases." (PMID 32425885, 2020).
LYPD3 also shares sentences with these, for which no sentence is quoted: pancreatic adenocarcinoma (3 papers); cervical squamous cell carcinoma (2); endocervical adenocarcinoma (2); lung squamous cell carcinoma (2); Acute Myelogenous Leukemia (1); adenocarcinoma (1); benign tumor (1); bladder cancer (1); cervical cancer (1); chronic pancreatitis (1); dysplasia (1); esophageal squamous cell carcinoma (1); invasive carcinoma (1); metastasis (1); metastatic cancers (1); non-small cell lung carcinoma (1); ovarian carcinoma (1); prostate carcinoma (1); pulmonary embolism (1); rectal cancer (1); renal cell carcinoma (1); testicular germ cell tumor (1); testicular germ cell tumours (1); urothelial cell carcinomas (1); urothelial hyperplasia (1); uterine sarcoma (1).